PARP1 (poly(ADP-ribose) polymerase 1)
Diseases named in the same sentence as PARP1 in open-access papers (continued):
Sharing a sentence is not in itself a finding about the gene and the disease.
tumor (continued). "An in vitro co‐culture of MM and NK cells assessed the effects of SMI‐16a (PIM‐2 inhibitor) and ABT888 (PARP1 inhibitor) on tumor proliferation and apoptosis, focusing on DNA damage, MICA expression, and NK cell functionality." (PMID 40557764, 2025). "Among various DNA repair factors, the overexpression of poly ADP-ribose polymerase-1 (PARP-1) family members in tumor cells has drawn particular attention." (PMID 40444043, 2025). "This delicate balance underscores the importance of context when evaluating PARP1's role as either an oncogene or a tumor suppressor." (PMID 40904702, 2025). "When PARP-1 becomes overactive, it disrupts the normal regulation of cellular processes such as cell division, apoptosis, and autophagy, optimizing tumor development and growth conditions." (PMID 40552150, 2025). "We demonstratedthat PARPi-MT, a Ru­(II)-based MT incorporating the PARP1inhibitor Olaparib as the binding motif, enables the spatial visualizationof PARP1 in murine brain and xenograft tumor tissues using both DESI-MSIand FI." (PMID 41341063, 2025). "In patient-derived xenograft models, B7-H4–directed ADCs combined with AZD5305, a selective PARP1 inhibitor, achieved complete tumor control, including in low antigen–expressing tumors." (PMID 41357243, 2025). "A proven strategy to disrupt DNA repair and sensitize tumor cells to radiation and chemotherapy is PARP1 inhibition." (PMID 41304780, 2025). "Fluzoparib’s high selectivity for PARP1/2 potently inhibits base excision repair, leading to accumulation of DNA double-strand breaks that cannot be repaired in HRR-deficient tumor cells." (PMID 41142243, 2025). "Analysis of TCGA database (accession number: phs000178) revealed increased PSI values for ACTA2, AREG, BRCA1, DDX5, MSH6, and PARP1 in tumor tissues compared to adjacent tissues." (PMID 39773744, 2025). "Tumor-derived sEVs are capable of effectively transporting CRISPR/Cas9 plasmids to tumor tissues, suppressing the expression of poly (ADP-ribose) polymerase-1 (PARP-1)." (PMID 40008006, 2025). "PARP1 is involved in DNA repair and gene expression, and inhibiting PARP1 has anti-tumor effects in AML." (PMID 40635996, 2025). "Inhibition of PARP1 has been shown to suppress tumor growth and metastasis, enhance the radiosensitivity and chemosensitivity of tumor cells, and modulate anti-tumor immune responses." (PMID 40713706, 2025). "Chemical inhibition of PARP1 has been demonstrated to decrease the proliferation and metastatic capacity of several types of tumor cells." (PMID 40661778, 2025). "Conversely, inhibiting PARP1 suppresses tumor growth through two mechanisms: inducing ferroptosis by repressing SLC7A11, or triggering pyroptosis via caspase-3-mediated gasdermin E cleavage." (PMID 41460301, 2025). "Further research showed that knockdown of PCNA significantly repressed the expression of PCNA and PARP1 in HepG2 xenograft tumor tissues." (PMID 40313621, 2025). "For instance, tumor-derived exosomes have been employed to deliver CRISPR/Cas9 systems targeting poly(ADP-ribose) polymerase 1 (PARP-1), yielding potent therapeutic outcomes in solid tumor models." (PMID 40948784, 2025). "Further, increased expression of cleaved‐PARP1 and decreased expression level of Bcl‐2 were detected in the tumor cells exposed to Bufalin." (PMID 40908551, 2025). "PARP-1 was found to play an important role in apoptosis, which is frequently dysregulated in tumor cells." (PMID 40725144, 2025).
tumor (continued). "Nevertheless, current studies on the application of PARP-1-targeting probes in tumor therapy remain limited, necessitating further research, exploration, and validation of their potential clinical value." (PMID 40444043, 2025). "CCK8, EdU, and colony formation assays demonstrated that PARP1 overexpression significantly reversed the inhibitory effects of MRPL21 knockdown on tumor cell proliferation." (PMID 40713706, 2025). "DUB3 depletion dramatically reduced YAP1 expressions while concurrently upregulated cleaved‐PARP1 levels in tumor samples from mice treated with saline." (PMID 39968498, 2025). "Olaparib, a potent PARP1 inhibitor, disrupts DNA repair in tumor cells and has been shown to induce CD8+ T-cell infiltration and activation and inhibit angiogenesis in BC." (PMID 40281554, 2025). "While we found a positive correlation between PARP1 expression and response to PARP inhibitors, which is in line with many in vitro studies, in patient tumours, the relationship between PARP1 expression and sensitivity to PARP inhibitors is more complicated." (PMID 40977519, 2025). "In HNSCC, the number of PARP1-positive tumor cells varies depending on tumor localization, with the highest levels found at the invasive margins rather than in the tumor core." (PMID 40864763, 2025). "We also found that CDK4/6 inhibition by abemaciclib dramatically reduced YAP1 expressions while concurrently upregulating cleaved‐poly(ADP‐ribose) polymerase‐1 (PARP1) levels in tumor samples from saline‐treated mice." (PMID 39968498, 2025). "Specifically, some genes were significantly modulated in all three tumors in the same way: AOX1, ENPP3, and NMRK2 were down-modulated in tumor specimens, whereas PARP1 was up-regulated." (PMID 38254798, 2024). "To further assess the effect of HMGA1 depletion on PARP1 inhibition, we tested the effect of olaparib on tumours generated from HMGA1‐manipulated AKR cells in a syngeneic mouse model." (PMID 39690136, 2024). "Previous researchers believed that PARP1 plays a crucial role in promoting the growth and proliferation of tumor cells." (PMID 38907095, 2024). "Promoting parthanatos in tumor cells by augmenting PARP-1 activity can impede tumor cell proliferation." (PMID 39620145, 2024). "Tumor uptake correlated with PARP1 expression levels, and despite high abdominal uptake due to hepatobiliary clearance, tumor contrast was sufficient, with a tumor/muscle ratio of 1.9 observed in the group with the highest PARP1 expression." (PMID 39768978, 2024). "Downregulating PARP-1 protein hinders the action of NF-κB and the expression of tumor-promoting proteins controlled by NF-κB, thereby preventing the induction of parthanatos." (PMID 39620145, 2024). "For example, saruparib demonstrated high selectivity for PARP-1, with anti-tumor efficacy in BRCAMUT mouse models of breast, colon, and pancreatic cancer, and reduced hematological toxicity." (PMID 39201718, 2024). "Meanwhile, selective inhibition of PARP1 by AZD5305 improved its IC50 potency by only 2.7-fold in SUM149PT tumor organoids." (PMID 39201277, 2024). "Specifically, HBV-DNA-Pol regulates PD-L1 transcription by repressing PARP1 nuclear translocation, which results in excessive PD-L1 expression in malignant hepatocytes, leading to PD-L1/PD-1 axis-mediated tumor immune evasion, and ultimately, HCC development." (PMID 38475878, 2024). "It has been shown that PARP1 upregulation enhances tumor resistance to apoptotic processes, contributing to the tumor’s resistance to various therapies, including chemotherapy and radiation therapy." (PMID 39598347, 2024). "An immunohistochemical study of PARP1 representation in human GBM sections revealed that it is upregulated in the nuclei of tumor cells." (PMID 39598347, 2024). "This specificity is crucial as itallowsprecise inhibition of PARP-1 in tumor cells with Breast Cancer 1 protein(BRCA1) or BRCA2 deficiencies." (PMID 39346823, 2024).
tumor (continued). "This scenario is supported by findings that the PARP1/2-specific, clinically used PARPi Olaparib inhibits tumor growth, and this effect is abolished when MΦs are depleted." (PMID 38612413, 2024). "Secondly, the overactivation of PARP‐1 activity contributes to the development of parthanatos and inhibits the proliferation of tumour cells." (PMID 38652105, 2024). "As such, PARP-1 modulates the tumor microenvironment by altering immune responses, chemokine expression, angiogenesis, and EMT." (PMID 39201718, 2024). "By inhibiting PARP1, these inhibitors prevent the repair of DNA damage induced by topotecan 18, leading to increased cytotoxicity in tumor cells." (PMID 39456202, 2024). "Increased expression of PARP1 is necessary for more efficient DNA damage repair due to the increased instability of the nuclear structure during uncontrolled tumor cell division and/or after radiation/chemotherapy treatments." (PMID 39595575, 2024). "Currently, PARPis are licensed in HER2-negative breast cancer only; however, aside from its role in DNA repair, PARP1 is known to influence tumor proliferation and HER2 resistance by co-activation of NF-κB." (PMID 38236558, 2024). "PRKDC, XRCC6, XRCC5 and PARP1 were significantly downregulated in tumor tissue of mice treated with ESCs and ESC-CM compared with those of mice treated with PBS." (PMID 38654216, 2024). "For example, Niraparib is a selective PARP-1 and PARP-2 inhibitor with favorable pharmacokinetics and anti-tumor roles in patients with BRCA1/2 mutations." (PMID 39588300, 2024). "CRISPR/Cas9 directed genome editing of tumor-derived exosomes inhibit poly (ADP-ribose) polymerase-1 levels and enhance the sensitivity of the SKOV3 xenograft mouse model to cisplatin; exosomes loaded with PARP-1 sgR/Cas9 reduce the tumor size in vivo." (PMID 38796525, 2024). "Taken together, according to our study, HBV DNA polymerase inhibits the nuclear translocation of PARP1 by interacting with PARP1, thereby upregulating the expression of PD-L1 in tumor cells at the transcriptional level." (PMID 38475878, 2024). "PARP1 expression seemed to be increased in all treatment groups compared to the untreated tumor except for the Rucaparib combination group." (PMID 39023784, 2024). "The primary pharmacodynamic effect (i.e., the direct consequence of the inhibition of PARP1/2 enzymes) of talazoparib was assessed by measuring PARylation levels within the tumor." (PMID 38010394, 2024). "Exposure of tumor cells to [123I]I-CC1 resulted in increased expression of PARP1 at 24 h after a 1 h exposure, with a cytotoxic effect on tumor growth in vitro and a less pronounced effect in PSN1." (PMID 38666920, 2024). "As previously indicated, the activity of PARP1 is particularly important in neoplasms where the homologous recombination (HR) DNA repair mechanism is compromised." (PMID 39195238, 2024). "To test the capacity of CeTEAM in live animals, we deployed the dual luminescence PARP1 biosensor system as a tumor xenograft model that to detect PARPi." (PMID 39643609, 2024). "As a key DNA repair enzyme, PARP-1 helps maintain genomic stability in tumor cells after treatment with DNA-damaging chemotherapeutic agents, thereby enhancing their survival." (PMID 39682189, 2024). "Beyond the well-established tumor marker PARP1, AOX1 can be a potential common therapeutic target for SCC treatment." (PMID 38254798, 2024). "This trial resulted from prior research by the same group which identified that HER2-positive tumors overexpress PARP1 and that PARPis induced tumor apoptosis in HER2-positive animal and cell line models irrespective of mutational status." (PMID 38236558, 2024). "Our study revealed that PINX1 maintains cellular DNA damage repair capacity independently of telomerase inhibition, introducing a new facet to PINX1’s function as a partner of PARP1, whose deletion sensitizes tumor cells to PARPi." (PMID 39174499, 2024).
tumor (continued). "In both CC‐LP‐1 and TFK‐1 tumour lysates, consistent with the tumour growth inhibition data, TE led to an increase in the expression of apoptosis‐related proteins, cleaved PARP‐1 or cleaved caspase‐3." (PMID 39223878, 2024). "Certain tumor types are vulnerable to inhibition of PARP1-mediated DNA repair as monotherapy or in combination with other treatments." (PMID 38383387, 2024). "The current landscape of clinical trials with PARPi is evaluating approaches to overcome tumor resistance and toxicity with new combination approaches and the use of next-generation PARPi that are selective to PARP-1." (PMID 39201718, 2024). "In an in vitro study on oral tumor cells, the administration of resveratrol and quercetin has been shown to induce oral tumor cell death due to DNA damage, PARP1 modification, and the upregulation of Bax." (PMID 38247942, 2024). "PARP-1 cleavage as a marker of apoptosis induction was clearly more pronounced in the testis tumor cells (showing the PARP-1 cleavage fragment), which is in line with the higher apoptotic response in this type of cells following cisplatin treatment." (PMID 37891379, 2024). "PARPi can kill tumor cells by inhibiting the PARP1 enzyme and trapping the PARP1-DNA complex to impedes ssDNA break repair." (PMID 39318358, 2024). "For instance, EVs derived from tumor cells have been used to deliver CRISPR/Cas9 plasmids to inhibit poly (ADP-ribose) polymerase-1 (PARP-1)." (PMID 39281673, 2024). "The patient participated in a clinical trial for SOMCL-9112 (PARP1 inhibitor) for 4 courses in August 2018 at Shanghai Cancer Hospital, and stopped taking this medication due to tumor propagation and severe myelosuppression." (PMID 39121276, 2024). "Santos revealed that the expression of PARP1 is related to tumor location (tumor of colon or rectum) and tumor stage (III/IV or I/II grade)." (PMID 38907095, 2024). "Accordingly, therapies aimed at pharmacological inhibition of PARP1 are considered promising for both tumor treatment and the therapy of neurodegenerative, diabetic, and cardiovascular diseases." (PMID 39595575, 2024). "There were increases in tumor uptake in a dose- and time-dependent manner following radiotherapy, which activates PARP1 in the similar manner." (PMID 39768978, 2024). "It was associated with ubiquitin-protein ligase E3 component N-recognin 5 (UBR5), PARP1, and ataxia-telangiectasia mutated interactor (ATMIN) in tumours, which are enriched in DNA damage and repair." (PMID 39451223, 2024). "As before, akaLuc luminescence effectively normalized PARP1 L713F-nLuc signals on a per-tumor basis." (PMID 39643609, 2024). "PARPi, which holds great promise as antitumor agents due to their ability to target PARP-1, a key factor contributing to tumor growth, increased malignancy, and the development of drug resistance." (PMID 38989152, 2024). "In HBV-associated HCC, HBV DNA polymerase inhibits the nuclear translocation of PARP1 by interacting with PARP1, thereby upregulating the expression of PD-L1 in tumor cells at the transcriptional level." (PMID 38475878, 2024). "PARPi entrapment of PARP1/2 causes DNA damage and cell death due to replication fork collapse and persistent PARP trapping in HR-deficient tumor cells." (PMID 39201277, 2024). "In GBM, PARP-1 expression has been found to be a distinct biomarker of tumor biological behavior and to correlate with poor outcome." (PMID 38666920, 2024). "For example, inhibition of PARP‐1 expression in epithelial cancers reduces tumour‐promoting proteins expressed by the NF‐κB pathway and reduces epithelial tumorigenesis." (PMID 38652105, 2024). "Collectively, our findings identify PINX1 as a multifaceted partner of PARP1, crucial for safeguarding cells against genotoxic stress and emerging as a potential candidate for targeted tumor therapy." (PMID 39174499, 2024). "AOX1, ENPP3, and NMRK2 were down-modulated in all analyzed tumor specimens, whereas PARP1 was up-regulated." (PMID 38254798, 2024).
tumor (continued). "Recent studies have demonstrated that the tumor susceptibility gene TSG101 binds to and enhances GR transcriptional activity and similarly, PARP1 drives enzymatic activity for DNA damage-induced IKK-NF-κB activation." (PMID 37087471, 2023). "survival times; correction rates of the DNA region spanning the -124C>T mutation in the TERT promoter of the combined tumor tissues; telomere length; expression levels of TERT, Ki67 and cleaved PARP1; cell proliferation assay." (PMID 37008065, 2023). "Since circTFDP2 binds to PARP1 and prevents it from cleavage, we examined PARP1 expression in our 50 paired of PCa tumour tissues and adjacent normal specimens using RT‐qPCR." (PMID 36597139, 2023). "The biological response of EAC-mice regarding the tumor volume, weight, and Caspase-independent apoptotic markers (PARP-1 and AIF) in response to free enzymes was assessed." (PMID 36627557, 2023). "This leads to increased PARP1 activity and inhibition of apoptosis, which in turn increases the likelihood of tumor recurrence." (PMID 37539980, 2023). "To further compare and validate the specific uptake of 68Ga-DOTA-Olaparib in different tumor models, we further selected the A549 models with lower PARP-1 expression for the 68Ga-DOTA-Olaparib biodistribution investigation (Figure." (PMID 37145164, 2023). "Western blot analysis of tumor lysates further confirmed that PARP1 cleavage was increased by d16 treatment." (PMID 37756561, 2023). "Second, in addition to its role in DNA damage repair, PARP1 is also involved in transcriptional regulation as a potent modulator of AR function and inducer of AR activity, and thus is involved in tumor proliferation." (PMID 37810962, 2023). "The combined therapy of abemaciclib and olaparib synergistically suppressed tumor growth in the xenograft model, and samples derived from animal tumors were used to confirm the key role of PARP1 in CDK4/6i resistance by immunohistochemical assay." (PMID 38037159, 2023). "In the TCGA database, we found that PARP1 was highly expressed in various tumours, including CCA (Supplementary 9A-B), and this result was also verified in the GSE107943 database (Supplementary 9C)." (PMID 37821935, 2023). "Immunohistochemistry staining of tumor tissue revealed a high expression level of PARP-1 in SK-OV-3 xenograft tissue." (PMID 37145164, 2023). "SKA3 overexpression accelerated tumour growth, while these changes were partly reversed by PARP1 and HIF-1a knockdown." (PMID 37821935, 2023). "Due to its connection with the DNA damage response, PARP-1 has become a promising target of tumor therapy, especially for breast and ovarian tumors." (PMID 36986843, 2023). "Regarding CRC, little is known about the importance of PARP-1 expression in this tumour, beyond its overexpression in regard to the normal mucosa and being correlated with disease progression." (PMID 36902215, 2023). "Our results on PARP-1 expression (Western blot and immunofluorescence) are consistent with these data, confirming its tumor-promoting "burden"." (PMID 37730576, 2023). "Total siRNA dose: 5 mg/kg.(+) PARP1 silencing confirmed by increased apoptosis, reduced tumor growth and increased mice overall survival." (PMID 37287910, 2023). "We identified that Bcl-2 and PARP1 protein expression was significantly downregulated in the CEP-inhibited tumor growth model, whereas Bax, Bad, cleaved caspase-3, and -9 protein expression was significantly upregulated." (PMID 38086844, 2023). "Then, the Olaparib derivatives were synthesized, radiolabelled, and evaluated in a PARP-1-positive tumor model." (PMID 37145164, 2023). "As a consequence, cells and tumours which are GSNOR-deficient are extremely sensitive to SDH inhibition, namely to α-tocopheryl succinate, a molecular targeting SDH, which induced RIP1/PARP1-mediated necroptosis and inhibited the growth of the tumour." (PMID 38098505, 2023).